CXCR3 (C-X-C motif chemokine receptor 3)
Diseases named in the same sentence as CXCR3 in open-access papers (continued):
Sharing a sentence is not in itself a finding about the gene and the disease.
tumor (continued). "Given that CXCR3 is the concomitant receptor for CXCL9, we leveraged our scRNAseq data to assess which tumor-associated immune cells could interact with our AAV encoded transgene." (PMID 38997283, 2024). "Similarly, BLT1(−/−) and CXCR3(−/−) mice showed a significant reduction in tumor-infiltrating CD8+ T cells as compared to their wild-type counterpart, despite similar frequencies of these cells in the periphery." (PMID 39596815, 2024). "CXCL9 binds to CXCR3 and mediates immune cell infiltration and activation in the tumor environment." (PMID 38245587, 2024). "In line with our hypothesis, in patients with low tumor burden (< 50%), CXCR3 + T cells were mainly present in the peripheral blood and not in the BM." (PMID 39613747, 2024). "Additionally, Treg cells can be recruited via CXCR3 and its associated ligands, which results in dampened effector T cell responses within the TME, fostering tumor growth and survival." (PMID 38786066, 2024). "The knockout of CXCR3 in mice resulted in significantly less CD8+ T cells infiltrating the tumor." (PMID 38928238, 2024). "However, the cellular densities determined in the flow cytometry experiment ranged from 1524 ± 579 CXCR3 + T cells/tumor (untreated control) to 9979 ± 6369 cells/tumor (2xICI treated)." (PMID 39196448, 2024). "Thus, our data demonstrate that CXCR3 is important for recruiting CD8+ T-cells from the tumour in order to get activated in the lungs." (PMID 38271469, 2024). "Furthermore, disrupting Treg’s CXCR3 boosted tumor CD8+ T cells and slowed cancer progression in solid tumor mouse models." (PMID 39596815, 2024). "Contrarily, ELR-CXCLs/CXCR3/4/5/6/7 signaling has mainly tumor suppressive effects." (PMID 39769501, 2024). "While induced by IFN-γ, low serum I-TAC levels seen in metastatic CRC cases may be explained by downstream CXCL11secretion, which produces opposite effects on tumor proliferation and metastases depending on the interacting ligands (CXCR3, CXCR7)." (PMID 38954024, 2024). "Furthermore, both the intrinsic antitumor properties of IRF1 and its ability to influence the formation of the tumor immune microenvironment through the IRF1/CXCL10/CXCR3 axis were demonstrated in hepatocellular carcinoma." (PMID 38396830, 2024). "Moreover, we found that CD8+ T cells were recruited by CXCL10 in vitro, whereas SCH546738, an inhibitor of CXCR3, inhibited T cell migration and splenocytes-mediated anti-tumor effect." (PMID 38953994, 2024). "However, CXCL10/CXCR3 signaling promotes tumor cell proliferation, angiogenesis, and metastasis when mediated by an autocrine pathway in tumor cells." (PMID 39273452, 2024). "Furthermore, the study found that when anti-CXCR3 antibodies were used in preclinical experimental settings, there was a consistent acceleration of tumor growth in mice that had B16-F10 tumor cells." (PMID 39273452, 2024). "In this study, higher levels of secreted CXCL10 in NCB patients may be reflective of pro-tumor activity due to overexpression of CXCR3 in the TME." (PMID 38236249, 2024). "However, tumor-specific T cells can also express both chemokine receptors (CXCR3 and CCR5), which suggests that the recruitment of bystander T cells is simply a collateral phenomenon accompanied by recruitment of tumor-specific T cells." (PMID 39669576, 2024). "The antitumor activity of CD3xTRP1 in CXCR3 KO mice was significantly impaired compared to their WT counterparts, indicating that therapeutic efficacy was at least partially dependent on T cells’ ability to home towards the tumor." (PMID 38167722, 2024). "This activation led to apoptosis in tumor cells through the CXCL10/CXCR3 paracrine axis." (PMID 38999981, 2024). "This may be due to significant increases in the calcium flux and ERK1/2 phosphorylation mediated by the CXCL10/CXCR3 pathway, which enhances tumor invasiveness." (PMID 39429695, 2024).
tumor (continued). "On the contrary, the recruitment of CXCR3-expressing T cells has been associated with an improved antitumor immunity, and IFNG and CXCL10 have been shown to inhibit the growth of MM cells, pointing towards a potential role in immune-mediated tumor control." (PMID 39613747, 2024). "However, IP-10 can also act the opposite way, when autocrine secretion and CXCL10/CXCR3 signaling by cancer cells support tumor cell proliferation, angiogenesis, and metastasis, inhibiting cancer cells’ apoptosis and immune response." (PMID 37509653, 2023). "Thus, the relationship between CXCL9, CXCL10, CXCL11/CXCR3 axis and tumor development or patient prognosis is still controversial." (PMID 38264648, 2023). "Together, the studies indicate tumor-specific T cells infiltrate PDA in a Cxcr3-independent manner." (PMID 36472588, 2023). "Moreover, our results also confirm that, in addition to tumor stage and grade, high CXCR3 expression correlates with a significant shorter time to recurrence of disease." (PMID 36831346, 2023). "To test this hypothesis, we quantified the percentage of each Cxcr3/Klrg1 subset that bound tetramer in KPC2a tumor-bearing mice." (PMID 36472588, 2023). "Cxcr3+ Klrg1-tetramer + T cells frequency progressively decreased in spleen and tumor over time." (PMID 36472588, 2023). "A. muciniphila can produce inosine, induce the expression of TH1 regulatory genes in CD4+ T cells, and reverse PD-1 blockade by IL-12 from dendritic cells, increasing the recruitment of CCR9+ CXCR3+ CD4+ T lymphocytes to the tumor microenvironment to kill tumor cells." (PMID 37416062, 2023). "However, it has been well documented that CXCL9, 10, and 11 play crucial roles in immune activation and tumor rejection in TME via its cognate receptor, CXCR312, and anti-tumor effect of anti-PD-1 therapy decreases in CXCR3 knock-out mice." (PMID 36991099, 2023). "Moreover, CXCL9, -10, -11/CXCR3 axis played an essential role in anti-PD-1 treatment, where anti-PD-1failed to inhibit the tumor growth with CXCR3 knockdown." (PMID 36860322, 2023). "In sum, our results support a role for Cxcr3 in the spleen to promote the differentiation of potent Gzmb + antitumor T cells that may aid in the control of tumor cell dissemination." (PMID 36472588, 2023). "Therefore, we assumed that the mechanism of ablation treatment enhancing anti-tumor immune response was regulated by the CXCL10/CXCR3 axis." (PMID 36900218, 2023). "The I-TAC is also capable of binding the CXCR3, leading to both pro- and anti-tumor activities." (PMID 37445908, 2023). "Further work is ongoing to corroborate our hypothesis-generating findings that the CXCR3 autocrine axis may drive tumor progression in HPVOPC and to elucidate the mechanisms by which it may interact with HPV proteins." (PMID 37686653, 2023). "Obstruction of CXCR3 resulted in reduced efficacy of PDOX to control tumor outgrowth." (PMID 36796366, 2023). "By concomitantly adding either CD8β-depleting or CXCR3-blocking antibodies to triple treatment, we found that both CD8+ and CXCR3+ cells were crucial for the abscopal effect as adding these antibodies completely attenuated abscopal tumor control and significantly worsened mouse survival." (PMID 37045833, 2023). "Thus, despite the accelerated antitumor response in Cxcr3+/+ mice bearing s.c. tumors, Cxcr3 was ultimately dispensable for tumor-specific T cell intratumoral accumulation in tumors growing within the skin." (PMID 36472588, 2023). "The expression of CXCR3 is relatively lower on T cells, B cells, and monocytes in the resting phase; however, CXCR3 is mainly expressed on the surface of T cells, B cells and NK cells in the activation phase and has the function of promoting tumor proliferation." (PMID 36782176, 2023). "Thus, Cxcr3, potentially through positioning of T cells in secondary lymphoid organs, promotes cytotoxic T cells likely capable of targeting metastatic tumor cells." (PMID 36472588, 2023).
tumor (continued). "The data above suggest that Cxcr3 and Klrg1 may define distinct T cell differentiation states during invasive tumor growth." (PMID 36472588, 2023). "However, CXCCL-9, CXCL10, and CXCR3 can have an opposite action in vivo where they increase tumor growth." (PMID 37296899, 2023). "These spots also upregulated the chemokines CXCL9 and CXCL12, which could attract T cells into the tumor via CXCR3 and CXCR4, respectively." (PMID 37655659, 2023). "We speculate that low expression of CXCR3 in T lymphocytes may reduce their recruitment into the tumor microenvironment." (PMID 36688994, 2023). "Notably, Cxcr3 blockade interfered with the frequency of splenic engineered T cells that expressed Granzyme B (GzmB), paralleling the defect in endogenous GzmB + tumor-specific T cells in Cxcr3−/− mice." (PMID 36472588, 2023). "The CXCL9, 10, 11/CXCR3 axis have both anti-tumor and pro-tumor activity." (PMID 37465363, 2023). "As cDC1s have been previously shown to produce Cxcr3 ligands in subcutaneous tumor models, we posited that the Cxcr3 pathway may play a role in tumor-specific T cell fate during pancreatic cancer growth and immunotherapy." (PMID 36472588, 2023). "The fact that the PI3K pathway is activated universally in T cells in response to IL-2 involvement may explain why IL-2 secreted by CD4+ T cells at the tumor site induces CXCR3 expression in various T- cell subsets." (PMID 38104126, 2023). "CXCR3 expression initiates tumor cell survival and metastasis through CXCR3 ligand expression." (PMID 36726488, 2023). "Similarly, the central role of CXCR3 chemokines in the tumor-targeting migration of antitumor effector T cells was also reported in adoptive T-cell transfer models." (PMID 36968220, 2023). "To test the hypothesis that Cxcr3 is critical for T cell migration into s.c. tumors, we implanted KPC2a tumor cells s.c. into Cxcr3+/+ or Cxcr3−/− mice." (PMID 36472588, 2023). "Thus, our study reveals a link between peripheral effector T cell differentiation and exhaustion in the tumor bed and tissue-specific roles for Cxcr3 on T cell differentiation and antitumor immunity." (PMID 36472588, 2023). "CXCR3 blocking after ACT prevented tumor infiltration of high-avidity tumor-specific T cells." (PMID 37280206, 2023). "However, tumor-specific T cells infiltrating primary tumors progressively downregulate both Cxcr3 and Klrg1 while upregulating exhaustion markers PD-1 and Lag-3." (PMID 36472588, 2023). "Tumor ulceration was delayed in Cxcr3−/− mice, which is consistent with a delay in tumor growth." (PMID 36472588, 2023). "Several studies reported that key chemokine receptors, especially CXCR3, may be required for tumor homing." (PMID 37280206, 2023). "However, they are often mismatched with each other, or tumor cells produce too few CXCR3 and CCR5 ligands, hindering T-cell trafficking and infiltration." (PMID 36765623, 2023). "Therefore, it is necessary to better investigate the mode of action(s) (MoAs) and related signaling pathways for CXCR3 given its potential role as a new target for clinical tumor immunotherapy." (PMID 37834457, 2023). "This can be explained by the varied expression patterns of CXCR3 in many tumor tissues." (PMID 37834457, 2023). "We believe that this distinction is critical for future research because, as in the case of tumor cells, each CXCR3 isoform might activate different downstream pathways with varied effects." (PMID 38104126, 2023). "An in vivo study compared the survival of tumor-bearing CXCR3-deficient and wild-type mice in an orthotopic GBM model, and found that the mice in the CXCR3-deficient group showed reduced recruitment of NK and natural killer T (NKT) cells and poorer median survival time." (PMID 38104126, 2023). "More than 60% of tumor-infiltrating CD8+ T cells expressed CXCR3 on their surface." (PMID 36479091, 2022).
tumor (continued). "This may be due to the anti-tumor response of CXCR3-signaling CD8+ T cells in the tumor microenvironment, which leads to a better prognosis of patients." (PMID 35847936, 2022). "CXCL10, CXCL11/CXCR3 axis can be used as the target of tumor immunotherapy." (PMID 35432485, 2022). "Since CXCR3 can bind to its ligands CXCL9, CXCL10, and CXCL11 to inhibit angiogenesis, CXCR3 may play an important role in wound healing and tumor growth." (PMID 36421704, 2022). "Significance of CXCR3 and its ligand pathway in different tumor immune environments." (PMID 36479091, 2022). "As for the genes regulated by EBV-miRNAs, the CXCL9, CXCL10, CXCL11/CXCR3 axis has been found to regulate immune cell migration, differentiation, leading to tumor suppression and may have potential role in cancer treatment." (PMID 36544484, 2022). "An in vivo preclinical study showed the inhibition of anti-PD-1 inhibitor effects in CXCR3 knockout mice, indicating that the homing of T cells to the tumor through the CXCL9,10,11/CXCR3 axis may be critical for anti-PD-1 inhibitor efficacy." (PMID 36289760, 2022). "Indeed, CXCL10 expression is enhanced by the combination therapy, thus promoting CXCR3-mediated cytotoxic T-lymphocyte infiltration and leading to a delay in hepatocarcinoma tumor growth." (PMID 36429101, 2022). "Third, our analysis is to evaluate the average CXCR3 activation levels of cancer patients, but CXCR3 activation in different regions of a tumor may be different due to tumor heterogeneity." (PMID 35562800, 2022). "To summarize, TDO2+ myofibroblasts were mainly located distally from tumor nests, and these cells attracted CD4+ T cells and CD8+ T cells through the CXCL9/CXCL10/CXCL11/CXCR3 axis, which may have prevented T cells from accessing tumor nests." (PMID 35972800, 2022). "Although these findings are instructive, the ability of CXCR3+ T lymphocytes and NK cells to exert endogenous tumor control may be compromised if there is long-term systemic antagonism of CXCR3 in the body’s internal environment." (PMID 36479091, 2022). "In addition, CXCL9- and CXCL10-expressing Macro-2 tumor cells interact with CXCR3-expressing proliferating T cells, Tregs, and CTL-1 cells in the tumor." (PMID 36180422, 2022). "In contrast, CXCR3 promotes tumor growth and metastasis while inhibiting tumor growth." (PMID 36479091, 2022). "Furthermore, the expression levels of CXCL9, CXCL10, CXCL11, and their receptor CXCR3, which perform anti-tumor roles in ICI treatment, were found to have increased in PTPRD/PTPRT mutant cancer patients." (PMID 36248841, 2022). "The mechanism of action of CXCR3 in various tumors may be uncovered, and it is expected to become a new target for clinical tumor immunotherapy." (PMID 36479091, 2022). "CXCR3 is expressed on activated NK cells and participates in physiological processes, such as enhancing NK cells cytotoxicity, promoting NK cell proliferation, and homing to tumor sites, through binding with its corresponding ligands." (PMID 36741396, 2022). "Our study demonstrates that CXCL10, a representative inflamed immune-response cytokine, activates CXCR3 in tumor cells to induce the phosphorylation of Src and the NF-κB subunit, p65, and the expression of HIF1-α in persistent EGFR-mutant tumor cells during EGFR-TKI treatment." (PMID 36612121, 2022). "Our data revealed that the addition of TIGIT blockade to MWA upregulated the expressions of CXCL9 and CXCL10 in TAMs and the expression of their receptor CXCR3 in T cells, which might restrain tumor growth and enhance antitumor immunity." (PMID 35320940, 2022). "Several studies have demonstrated the anti-tumor effects of CXCR3 and its ligands." (PMID 36479091, 2022). "Our study suggests that tubulin inhibitors may “heat” the tumor immune microenvironment by activating the CXCR3 pathway, thereby improving the efficacy of ICI therapy." (PMID 35562800, 2022).
tumor (continued). "The CAF-mediated reduction in CXCR3 expression on T cells could incapacitate an efficient migration towards tumor nests, which may be of particular importance in PDAC due to its high content of CAF-rich stroma." (PMID 35954489, 2022). "With further research on the critical role of the tumor environment in the immune system, it was found that CXCR3 and its ligands may exert anti-tumor effects by mediating chemotaxis and inhibiting angiogenesis." (PMID 36479091, 2022). "CXCR3 plays a crucial role in migrating effector T cells to inflammation and tumor sites." (PMID 36479091, 2022). "This suggests that CAFs may contribute to the entrapment of T cells in the desmoplastic stroma by disabling CXCR3 ligation and hence a migration towards the tumor nests." (PMID 35954489, 2022). "Most of the ligands of CXCR3 in the ELR− family possess tumor-suppressor functions." (PMID 35269786, 2022). "CXCR3 is also expressed in some tumor cells and vascular endothelium." (PMID 36479091, 2022). "In colorectal tumors, CXCR3 is mainly expressed in the cytoplasm and cell membrane of tumor cells." (PMID 36479091, 2022). "We, therefore, hypothesize that CXCL9/10 signaling via CXCR3 may impact the microenvironment and potentially promote tumor progression through deregulation of inflammatory pathways." (PMID 36180422, 2022). "The role of CXCR3 in tumor progression involves a complex signaling cascade." (PMID 36479091, 2022). "Regarding the tumors, it has been well studied that CXCL9/10/11 (ligands for CXCR3) produced by macrophages and DCs, along with CCL5 (ligands for CCR5) secreted by tumor cells, are associated with T cell recruitment to the TME and a favorable response to chemotherapy and immunotherapy." (PMID 35925680, 2022). "Thus, elucidating a more profound role for CXCR3 requires a broader assessment of the impact of receptor targeting on potential anti-tumor immune effector cell functions." (PMID 36479091, 2022). "The roles of CXCR3 in tumor progression or inhibition have been reported in recent studies." (PMID 35562800, 2022). "CXCR3 and its ligands also play crucial roles in tumor metastasis." (PMID 36479091, 2022). "However, in line with the observations above, when CAFs were added to the cultures together with tumor spheroids, a decrease in CXCR3 expression and an increase in CXCR4 expression was observed in CD8+ T cells." (PMID 35954489, 2022). "However, the expression of CD45RA, CD27, and CXCR3 increased, indicating that stem cell memory T cells were genuinely differentiated and thus exhibited stronger anti-tumor immunity." (PMID 36479091, 2022). "Metagenomics based on stool samples from cancer patients at the time of diagnosis reveals a correlation between clinical response to immune checkpoint inhibitors and the relative abundance of A. muciniphila recruitment of CCR9 + CXCR3 + CD4 + T lymphocytes into the mouse tumor bed." (PMID 35774450, 2022). "Together with their receptor, CXCR3, they might be involved in tumor elimination by inhibiting angiogenesis and recruiting immune and inflammatory cells to engage tumors in mortal combat." (PMID 36164329, 2022). "It includes receptors that have been mechanistically linked to cancer progression such as the G protein coupled receptors CXCR3 and FZD6, linked to tumor cell growth, invasion and migration, and PTPN22, a protein tyrosine phosphatase associated with inhibition of antioncogenic immune response." (PMID 35875157, 2022). "Immunogenicity analysis showed the CXCR3-high group had higher tumor neoantigen burden (TNB)." (PMID 35562800, 2022). "The relationship between the CXCL9,10,11/CXCR3 pathways and PD-1/PD-L1 is a vital area of research, and combining this pathway with other immunotherapies improves the efficacy of tumor immunotherapy by enhancing the inhibition of tumor progression through multiple mechanisms." (PMID 36479091, 2022).